IL10 (interleukin 10)
Diseases named in the same sentence as IL10 in open-access papers (continued):
Sharing a sentence is not in itself a finding about the gene and the disease.
leptospirosis (continued). "Our results suggest determining and balancing [delete] the level of TNF-α and IL-10 in patient’s serum as useful prognostic factors in leptospirosis patients." (PMID 35919644, 2022). "Our results showed that the levels of TNF-α and IL-10 significantly increased in severe leptospirosis." (PMID 35919644, 2022). "In contrast, IL-10 is thought to be the most important anti-inflammatory cytokine which restores the immunological homeostasis in leptospirosis." (PMID 32264832, 2020). "IL-10 was reported to reach a peak within 1–5 days postinfection in a recent study among leptospirosis patients." (PMID 30123395, 2018). "IL-4, IL-6, IL-8, IL-10, IL-17A, and TNF-α levels in severe leptospirosis compared to mild disease, and an association between high IL-6, IL-8, IL-10 and fatal outcome." (PMID 26824356, 2016). "In an animal model of leptospirosis, genes for both pro- and anti-inflammatory cytokines, including tnfalpha, il1alpha, cox2 and il10, were significantly upregulated in the blood of dead compared with recovered hamsters." (PMID 26146835, 2015). "In the case of leptospirosis, it was observed that the induction of IL-10 is higher in mice than in hamsters animal model, consistent with the chronically, asymptomatic nature of this model." (PMID 25110682, 2014). "In univariate analysis, fatalities from SPHS had higher levels of IL-6, IL-8, and IL-10 in comparison to fatalities from other leptospirosis-related complications (P<0.05)." (PMID 24069500, 2013). "The control dogs of Study 2 were asymptomatic, yet showed high levels of IL-10 PC, which may suggest that IL-10 has a protective effect in acute leptospirosis." (PMID 40732660, 2025). "Also, it has been reported that interleukin-10 has been suggested to play a complex role in canine leptospirosis, potentially contributing to the disease’s severity and outcome." (PMID 40732660, 2025). "Severe leptospirosis may trigger a cytokine storm, characterized by elevated serum levels of IL-6, IL-10, and TNF-alpha, indicating widespread dissemination of the pathogen." (PMID 38398036, 2024). "However, due to the lack of enough studies in this field, more studies are needed to target IL-10 in the treatment of the severe forms of the leptospirosis." (PMID 35919644, 2022). "Altogether, these findings suggest that IL-10 could either be protective by counterbalancing pro-inflammatory cytokines during the early stage of the disease, or have harmful effect in the leptospirosis outcome acting on bacterial burden." (PMID 29974037, 2018). "Furthermore, there was a thread of increase in IL-10 (30.68 pg/ml ± 33.2) and IL-17A (11.66 pg/ml ± 5.4) in the leptospirosis group compared to the healthy group." (PMID 30123395, 2018). "Thus, IL-10 contribution in leptospirosis pathophysiology probably depends on the stage and severity of the disease." (PMID 29974037, 2018). "However, asymptomatic leptospirosis presented an anti-inflammatory response with higher IL-10-producing CD4+ T-cells compared to patients with severe or mild leptospirosis." (PMID 29974037, 2018). "Leptospirosis-associated pulmonary hemorrhage was not characterized by a specific pattern, with only mild changes noted, including increased IL-10 and decreased 5-LO expression on some days in affected dogs." (PMID 26824356, 2016). "Leptospirosis-susceptible hamsters showed strong expression of IL-1β, IL-6, TNF-α, and COX-2 in infected organs, whereas leptospirosis-resistant mice showed accelerated expression of the anti-inflammatory IL-10." (PMID 26824356, 2016). "This study shows that severe cases of leptospirosis are differentiated from mild disease by a “cytokine storm” process, and that IL-6 and IL-10 may play an immunopathogenic role in the development of life-threatening outcomes in human leptospirosis." (PMID 24069500, 2013).
leptospirosis (continued). "A high IL-10/TNFα ratio was reported as correlated with poor outcome in septic patients, contrary to the opposite results obtained in one limited study reported in leptospirosis." (PMID 20076757, 2010). "Thus, induction of IL-4 and IL-10 might play an important role in leptospirosis pathophysiology that still needs to be precisely described." (PMID 29974037, 2018). "However, up-regulation of the IL-12b gene of HBMs may not further induce IFN-γ expression in CD4+ T cells during human leptospirosis, since IL-10 in HBMs was also up-regulated and the high-level of IL-10 could suppress the immune response." (PMID 24130911, 2013). "In severe leptospirosis, TNF-α and IL-10 levels increase, with IL-10 significantly higher in fatal cases." (PMID 40732660, 2025). "It has been noted that there was a high IL10: TNF-α ratio in the control dogs experiencing acute leptospirosis, as was also reportedly found in human patients with fatal outcomes of acute leptospirosis." (PMID 40732660, 2025). "Immune simulation results indicated significant increases in B and Th-cell populations, with elevated levels of TGF-β, IL-10, and IFN-γ, essential for managing inflammation and controlling leptospirosis." (PMID 39936152, 2024). "Significantly higher concentrations of IL-1β, IL-2, IL-4, IL-6, IL-8, IL-10, IL-17A, and TNF-α were found in sera of leptospirosis patients." (PMID 35927283, 2022). "Several earlier studies have identified significant expression of IL-1β, IL-2, IL-4, IL-6, IL-8, IL-10 and TNF-α in severe leptospirosis." (PMID 35584087, 2022). "In severe leptospirosis in humans, two scenarios have been reported; either high IL-10 and low TNF-α or low IL-10 and high TNF-α." (PMID 35584087, 2022). "In patients with severe leptospirosis and pulmonary involvement, elevated levels of IL-6, CXCL8, and IL-10 were obtained when compared to patients with mild leptospirosis." (PMID 35203344, 2022). "Especially, TNF-α and the interleukins IL-1β, IL-2, IL-4, IL-6, IL-8, and IL-10 were elevated in severe leptospirosis cases, whereas TNF-α, IL-6, IL-8, IL-10, interferon-γ, and soluble TNF receptor 1 were elevated in high fatality cases." (PMID 35237527, 2021). "Several host mediators have been investigated as potential biomarkers of leptospirosis, such as human serum (mannose binding lectin, MBL), interleukin 6 (IL-6), IL8, IL-10, soluble suppression of tumorigenicity 2 receptor, pentraxin 3, and copeptin." (PMID 35237527, 2021). "Fatal outcomes from Plasmodium falciparum malaria showed elevated levels of IL-6, IL-10 and TNF-α than in survival which was comparable to the results on leptospirosis." (PMID 32264832, 2020). "Although, the review produced valuable data on the possible role of cytokines in leptospirosis disease severity, there were equivocal findings with regards to IL-1β, TNF-α and IL-10/TNF- α ratio among the selected studies." (PMID 32264832, 2020). "IL-1b, IL-2, IL-4, IL-6, IL-8, IL-10 and TNF-α levels were found to be significantly higher in severe than in mild leptospirosis." (PMID 32264832, 2020). "Elevation of serum IL-10 and IL-17A levels and significant elevation of serum IL-21 (p=0.002), IL-23 (p=0.002), and TNF-α (p=0.039) were observed among leptospirosis patients compared to the healthy control group." (PMID 30123395, 2018). "The serum cytokine levels of IL-10, IL-17A, IL-21, IL-23, and TNF-α were investigated in 57 patients with leptospirosis and 12 healthy controls using a commercially available ELISA kit (Mabtech, Sweden)." (PMID 30123395, 2018). "Leptospirosis cases with fatal outcomes exhibited higher IL-10 but lower TNF-α levels than survivors, and a positive correlation was identified between the IL-10/TNF-α ratio and fatal outcomes." (PMID 26146835, 2015).
leptospirosis (continued). "Dysfunctional regulation of the levels of the cytokines/chemokines IL-6, IL-8, IL-10, IFN-ɣ, KC/GRO, MCP-1, MIP-1a, MIP-2 and TNF-α, after infection of C3H/HeJ mice with virulent Leptospira, were correlated to the severity of leptospirosis observed in this animal model." (PMID 39312584, 2024). "Similar to the present review, IL-6, IL-8, IL-10, IP-10, MCP-1, TNF-α and VEGF were found to be elevated in DHF, a condition common to almost all endemic settings for leptospirosis." (PMID 32264832, 2020). "Serum levels of pro-inflammatory IL-6, chemokine IL-8 and anti-inflammatory IL-10 were significantly higher among patients that developed SPHS compared to non-SPHS leptospirosis patients." (PMID 29974037, 2018). "The cytokine profile revealed that the levels of at least sixteen cytokines were significantly elevated in the leptospirosis patients’ sera, including the major proinflammatory factors IL-1β, IL-6 and TNF-α, and the major anti-inflammatory factors IL-4, IL-10 and IL-13." (PMID 22870312, 2012). "In conclusion, severe leptospirosis due to the L. interrogans strain HP358 could be characterized as a sudden and increased pro-inflammatory response with delayed and significantly low expression of anti-inflammatory IL-10." (PMID 35584087, 2022). "Additionally, in human leptospirosis, contradictory findings showed either greater IL-10 levels or no significant change in IL-10 levels." (PMID 36551258, 2022). "Notably, we observed the secretion/mRNA expression of several cytokines (IL6, IL8, IL-1β, TNFα, IFNγ, IL10, CCL2/MCP-1, CCL10, COX2, CXCL1/KC, CXCL2/MIP2) and immune effectors (hBD2, iNOS, Fibronectin, Oxygen, and Nitrogen reactive species) as key aspects of host TLR2 responses during leptospirosis." (PMID 39729468, 2024). "For this, we evaluated the mRNA expression of a panel of immune related cytokines (IL-1α, IL-1β, IL-8, IL-10, TNF-α, TGF-β) and enzymes (5-LO, iNOS) in blood leukocytes from dogs with AKI and leptospirosis, including dogs with and without LAPH." (PMID 26824356, 2016).
lupus nephritis (31 papers, 2011 to 2025). Glomerulonephritis in the context of systemic lupus erythematosus. "Significantly increased expression of cytokines in the glomerulus, including IFN-γ, IL-12, IL-18 and IL-10, was correlated with disease activity indices in patients with lupus nephritis." (PMID 39478861, 2024). "Patients with lupus nephritis had a significantly decreased in circulating IL-10+ Bregs levels compared to health controls." (PMID 37771588, 2023). "IL-10 attenuates kidney injury in several models of kidney diseases, including lupus nephritis, cisplatin nephrotoxicity, complex immune nephritis, ischemia-reperfusion injury, and transplantation." (PMID 36013329, 2022). "This study is promising as a prophylactic tailored experimental lupus nephritis therapy, using the approach of self-epitopes derived from Sm antigen, co-vaccinated using opposite cytokines: the critical molecule in lupus nephritis IFN-γ vs. IL-10." (PMID 34705865, 2021). "Along this line, IL-10-producing B cells were unable to prevent the clinical course of lupus nephritis in MRL/lpr mice, indicating that B cell-derived IL-10 has no immunosuppressive function in GN." (PMID 33496881, 2021). "One report described Breg cells as protective, as the transfer of in vitro anti-CD40-generated B cells greatly improved lupus nephritis through an IL-10-dependent mechanism." (PMID 33240280, 2020). "A decrease in IL-10 secretion is indicative of a decrease in the body's negative immunomodulatory capacity, leading to B cell activation and progression of lupus nephritis." (PMID 31240224, 2019). "The proportion of renal pathological IL-10+ B cells in patients with lupus nephritis (LN) was significantly lower than that in healthy controls." (PMID 31240224, 2019). "The M2c-like subtype is further driven by IL-10, a cytokine that is highly upregulated in patients with lupus nephritis, suggesting this macrophage subtype is highly relevant in this disease." (PMID 27091114, 2016). "Proinflammatory chemokines (MCP-1) and cytokines (IL-6, TNF-α), Th1 cytokines (IL-2, IFN-γ), Th2 cytokines (IL-4, IL-10), and Th17 cytokines (IL-17A) are involved in pathogenesis of lupus nephritis, and are therapeutic targets for lupus nephritis." (PMID 27846813, 2016). "Additionally, in lupus nephritis patients it has been shown both decreased production of IL-10 and inability of IL-10+ B cells to suppress CD4+ T cell cytokine production." (PMID 40761803, 2025). "Furthermore, we observed that the functional defect of IL-10+ Tr1-like cells in pediatric patients with lupus nephritis can be restored by corticosteroid treatment." (PMID 37771588, 2023). "Similarly, although a high percentage of IL-10 secreting cells has been noted in patients with lupus nephritis, in vitro treatment of their peripheral blood mononuclear cells with anti-OX40 therapy reduces IL-10 expression." (PMID 31597242, 2019). "However, a recent report demonstrated a decrease in IL-10-producing B cells in lupus nephritis patients compared to healthy controls, reflecting an impaired regulatory function of those cells too." (PMID 31871930, 2019). "Stimulation with CD134-Fc fusion protein further reduced the production of both Th1 and Th2 cytokines including IL-4, IL-10, and IFNγ in patients with lupus nephritis, suggesting the potential role of anti-CD134 in reducing IL-4- and IL-10-mediated renal inflammation." (PMID 24000287, 2013). "In addition, increased IL-10 production was observed in lupus nephritis patients." (PMID 30944545, 2019). "Bregs are characterised by the release of IL-10, and the capacity of CD19+ B cells to release IL-10 is significantly reduced in patients with SLE, especially in those with lupus nephritis." (PMID 37500293, 2023). "The IL-10+ Bregs in patients with SLE decreased compared with those in normal subjects, especially in SLE patients with lupus nephritis." (PMID 31240224, 2019).
lupus nephritis (continued). "As IL-10 promotes glomerular damage by increasing mesangial proliferation and the mesangial deposition of immune complexes, our results suggested that the TLR7-dependent production of IL-10 in glomerular patrolling monocytes promotes lupus nephritis." (PMID 34868046, 2021). "IL-9 and IL-10 showed a significant positive correlation with IL-25 in all 17 SLE patients with lupus nephritis, whereas a significant negative correlation was observed with IL-5 and IL-6." (PMID 31697750, 2019). "Coincidently, neither IL-10+/− nor IFNγ+/− MRL/lpr had altered autoantibody titers, while the loss of one allele resulted in worsened or attenuated lupus nephritis, respectively." (PMID 31311609, 2019). "IL-10 showed a significant positive correlation with IL-25 in all 47 SLE patients without lupus nephritis, whereas a significant negative correlation was observed with IL-5." (PMID 31697750, 2019). "Less TNFSF4 may lead to induction of IL-10-producing CD4(+) type 1 regulatory T (Tr1) cells, while higher IL-10 was an intrarenal biomarker of disease activity in lupus nephritis." (PMID 23936824, 2013). "Thus, the aim of this research is to determine the plasma levels of IL-25 and Th2-associated cytokines (IL-4, IL-5, IL-6, IL-9, IL-10, IL-13) in SLE patients with (SLE-LN) and without lupus nephritis." (PMID 31697750, 2019). "As a matter of fact, LPS or apoptotic cells alone could promote IL10 secretion in MZ B cells, while in MRL-Faslpr/lpr mice, specific depletion of IL10 in CD19+ B cells does not exacerbate lupus nephritis." (PMID 26068236, 2015). "IL-9 and IL-10 showed a significant positive correlation with IL-25 in 64 patients of SLE with and without lupus nephritis." (PMID 31697750, 2019).
neuropathy (31 papers, 2010 to 2025). A disorder affecting the nervous system that manifests with pain, tingling, numbness, and/or muscle weakness. "Elevated levels of both IL-6 and IL-10 were associated with reduced neuropathy in experimental animals." (PMID 26090964, 2015). "Similarly, in this study both IL-6 and IL-10 were inversely associated with neurological signs of tremor and neuropathy." (PMID 26090964, 2015). "In patients with different neuropathies, levels of IL-10 have been described downregulated in serum and CSF and negatively correlating with pain scores, therefore suggesting an increased systemic inflammation." (PMID 36860843, 2023). "Total calcium, tumor necrosis factor-α (TNF-α), interleukin-6 (IL-6), interleukin-10 (IL-10), myeloperoxidase, and severe neurodegeneration were also examined, as they were strongly associated with VCR-induced neuropathy in animal models." (PMID 37107178, 2023). "Decreased expression in immunosuppressive cytokines like interleukin-4 (IL-4) or interleukin-10 (IL-10) is also significant between pain and painless neuropathy." (PMID 38026483, 2023). "Our results are in accordance with previous studies where higher levels of IL-10 were reported in serum from patients with neuropathies." (PMID 36860843, 2023). "A recent study has also found a significant decrease in the neuropathy severity, a decrease in the IL-6 level and an increase in the IL-10 level after treatment with cholecalciferol (40,000 IU/week) for 24 weeks in patients with T2DM and DPN." (PMID 33777989, 2021). "Peripheral LPS-stimulated brain produced a very low amount of IL-10 (1–4 pg/mg brain protein), but the minute IL-10 confers significant microglial neuroprotective abilities to alleviate multiply neuropathies." (PMID 34571824, 2021). "Our finding supported that CTSS inhibition results in an anti-inflammatory response in oxaliplatin-induced neuropathy, through the upregulation of IL-10." (PMID 33754020, 2021). "DRG from PAE rats with neuropathy reveal significant increases in satellite glial activation and IL-1β, while IL-10 immunoreactivity is reduced by half in PAE rats under basal and neuropathic conditions." (PMID 30961664, 2019). "Both IL-6 and IL-10 high levels have been described to be responsible for the neuropathy decline in T. brucei." (PMID 31687034, 2019). "This suggests that the higher expression of IL-10 might act as a compensatory mechanism against the inflammation triggered by neuropathy-specific processes." (PMID 36860843, 2023). "Notably, we showed recently that the spontaneous resolution of cisplatin-induced neuropathy is dependent on IL10 signaling as well." (PMID 35093182, 2022). "It remains to be determined whether IL10 signaling is involved in the slowly developing but persistent reversal of established cisplatin-induced neuropathy." (PMID 35093182, 2022). "Protective functions in the pathogenesis of neuropathy have been attributed to IL-10." (PMID 34681732, 2021). "An RCT study of 67 patients of DM II with neuropathy and administration of Vitamin D 40,000 IU weekly revealed improvement of symptoms and decrease in interleukin-6 (IL-6) and elevation of interleukin-10 (IL-10)." (PMID 34567869, 2021). "IL-10 inhibits the release of IL-1β and IL-6 and plays role in neuropathy." (PMID 26090236, 2015). "Treatment with IL-10 or TNF-α, IL-1, and IL-6 receptor antagonists substantially mitigates allodynia and hyperalgesia in neuropathy animal models." (PMID 37107178, 2023). "The elevated IL-10 immunoreactivity in Sac rats with CCI suggests the increase occurs in response to minor damage, possibly to maintain homeostasis and consequent non-neuropathy." (PMID 30961664, 2019). "However, nerve cells can mitigate nerve damage and neuropathy by producing anti-inflammatory cytokines such as transforming growth factor-β (TGF-β), IL-4, IL-10, and IL-13." (PMID 40718454, 2025).